IL1B (interleukin 1 beta)
Diseases named in the same sentence as IL1B in open-access papers (continued):
Sharing a sentence is not in itself a finding about the gene and the disease.
gingivitis (continued). "On the other hand, we were not able to detect any impact of 14 days of oral hygiene neglect on the salivary IL-1β, IL-8, MIF, or MCP-1 levels in either the placebo or the probiotics groups, which is contrary to our earlier study where IL-1β, IL-8, and MCP-1 decreased during experimental gingivitis." (PMID 38004199, 2023). "Only one study reported the effect of mechanical treatment on gingivitis control measures by cytokines levels, and the results showed that, although reduction of inflammatory process occurs, the levels of IL-1β, IL-6, and IL-8 remain high compared to subjects without CP." (PMID 33717115, 2021). "It was shown that tongue cleaning, which might lead to a reduction of microbial colonization, correlated with decreased levels of IL-1β and IL-8 in GCF in patients with gingivitis, suggesting that “health” of one oral niche can even lead to less inflammation in other oral niches." (PMID 33153049, 2020). "It is therefore interesting that VEGF and IL-1β were not significantly decreased until 10 days after oral hygiene discontinuation, when the majority of the participants had developed moderate to severe gingivitis." (PMID 28839521, 2017). "However, in other studies where the results showed that IL-1b was higher in the crevicular fluid of patients with gingivitis, the results were not statistically significant." (PMID 24790719, 2014). "This cohort study aimed to compare the effect of ultrasonic scaling on the expression of IL-1β in the gingival crevicular fluid (GCF) among ENDS users and non-smokers (NS) with gingivitis." (PMID 38988743, 2024). "There is a paucity of evidence comparing the effect of ultrasonic scaling on the expression of inflammatory biomarkers, like IL-1β, between ENDS users and non-smokers (NS) among young adults with gingivitis." (PMID 38988743, 2024).
diabetic nephropathy (83 papers, 2012 to 2025). "IL-1β is linked to diabetic nephropathy, cardiovascular complications, and conditions like polymyalgia." (PMID 40332476, 2025). "Activation of NALP3 inflammasome and secretion of IL-1β and IL-18 causes the development of tubulointerstitial disease in diabetic nephropathy." (PMID 30876398, 2019). "IL1B showed a significant association with risk of diabetic nephropathy having an OR of 1.97 (95% CI 1.22-3.18)." (PMID 25280384, 2014). "In this meta-analysis, there is only one study showing allele IL1B*2 associated with a nearly two fold higher risk of diabetic nephropathy." (PMID 25280384, 2014). "Numerous studies have demonstrated that MCP1 and IL-1β participate in different inflammatory states associated with renal diseases, including ischaemia/reperfusion injury, kidney transplantation, diabetic nephropathy, and hypertensive renal damage." (PMID 26450610, 2015). "Numerous studies have demonstrated that tumor necrosis factor-α (TNF-α), MCP-1 and interleukin-1β (IL-1β) participate in different inflammatory states associated with renal diseases, including ischaemia/reperfusion injury, kidney transplantation, diabetic nephropathy and hypertensive renal damage." (PMID 27129290, 2016). "Inflammation is of special importance in pathologies such as diabetic kidney disease, hence the extent of response to IL-1β, diabetic milieu and TGFβ1 stimulation was deemed interesting to explore." (PMID 41023975, 2025). "For example, both IL-1β and TNF-α are released in high concentrations in IRI, and IL-1β is known to promote renal steatosis in models of diabetic nephropathy through upregulation of SREBP1 in an NLRP3-dependent fashion." (PMID 38464721, 2024). "Both IL-1b and IL-6 are elevated in several forms of inflammatory chronic kidney diseases, including diabetic kidney disease." (PMID 39334814, 2024). "As per the clinical data, the levels of IL-6 and IL-1β were increased in patients with diabetic nephropathy." (PMID 38202711, 2023). "Another study based on ursolic acid reported that immunohistochemical staining revealed a rise in the expression of cytokines such as TNF-α, MCP-1, and IL-1β in diabetic nephropathy rats compared to control animals." (PMID 38202711, 2023). "In addtion, IHC staining also revealed that TNF-α, IL-1β and IL-6 signifificantly increased in diabetic nephropathy kidney, its secretion can be suppressed by treatment of A&P." (PMID 35057768, 2022). "According to clinical data, the concentration of IL-1β and IL-6 was increased in patients with diabetic nephropathy." (PMID 35956936, 2022). "Various inflammatory stimuli, such as TNF-α, CCL-2, IL-1β, and IL-6, which drive chronic renal inflammation in diabetic kidney disease, have been shown to stimulate Saa3 production in mice." (PMID 35055081, 2022). "MALAT1 overexpression catalyzed pyroptosis in diabetic nephropathy to accelerate kidney impairment with the involvement of increased IL‐1β, IL‐18, Caspase-1, and GSDMD." (PMID 36243708, 2022). "Caffeic acid also had anti-inflammatory effects in the model of diabetic nephropathy (DN) mice by reducing renal IL-6, IL-1β, TNF-α, and MCP-1 levels." (PMID 35052518, 2021). "In streptozotocin-induced diabetic nephropathy rats, chronic pioglitazone treatment reduced renal NFκB, IL-1β and IL-18 levels, depressed the glomerular mesangial expansion, and decreased serum BUN/creatinine." (PMID 34831270, 2021). "To further confirm the role of metformin in inflammation under diabetic nephropathy, we detected the expression of IL-1β in renal tissue." (PMID 34628484, 2021). "Inhibition of IL-1β secretion by zerumbone has also been reported in streptozotocin-induced diabetic nephropathy and LPS-induced acute lung injury animal models." (PMID 34045963, 2021).
diabetic nephropathy (continued). "NF-κB promotes inflammatory cytokines (e.g., IL-6, IL-1β) production to exacerbate renal inflammation associated with acute kidney injury (AKI) and diabetic nephropathy, which is largely suppressed by JSH-23 (NF-κB inhibitor)." (PMID 32512831, 2020). "Immunostaining of such kidney biopsies across a broad spectrum of diabetic kidney disease stages revealed IL-1β positivity in a small subset of infiltrating immune cell." (PMID 31191559, 2019). "IL-1β and IL-18 appear to contribute to the progression of renal damage during diabetic nephropathy." (PMID 31540220, 2019). "We microdissected glomerular and tubulointerstitial samples from kidney biopsies of patients with diabetic kidney disease and found expression of IL-1β mRNA." (PMID 31191559, 2019). "Here we showed that the IL-1β was significantly upregulated in the early stage of diabetic nephropathy, and the expression of IL-1β in glomerular mesangial cells was induced by high glucose and lipopolysaccharide in a dose-dependent and time-dependent manner." (PMID 26881256, 2016). "Recent randomized clinical trials demonstrated that the level of IL-1β level was significantly increased in and positively correlated with renal function injury in patients with diabetic nephropathy." (PMID 26881256, 2016). "A dose-finding trial of the anti-IL-1β antibody gevokizumab in diabetic kidney disease will start in 2015." (PMID 26239562, 2015). "For instance, NF‐κB phosphorylation in renal tissues of mice with diabetic nephropathy and high glucose‐treated renal tubular epithelial cells promoted the release of IL‐1β and IL‐18, activating macrophages in the renal mesenchyme and aggravating tubular injury." (PMID 40391402, 2025). "In addition, apigenin-solid lipid nanoparticles (SLNPs) to reduce renal mRNA expression levels of IL-6, TNF-α, and IL-1β in streptozotocin-induced diabetic nephropathy rats." (PMID 36422572, 2022). "Besides chemokines, the over expression of several inflammatory cytokines, such as IL1β and TNFα, have been identified as biomarkers in diabetic kidney disease." (PMID 35782913, 2022). "We specifically aimed at assessing the interference of SGLT2 inhibition with tubular inflammatory response mechanisms that are essential for the initial pathogenesis of both diabetic and non-diabetic nephropathies, by utilizing IL-1β as a pro-inflammatory ligand and Empa." (PMID 33139635, 2020). "NLRP3, IL-1β, and IL-18 in rats with diabetic nephropathy were markedly increased." (PMID 30555415, 2018). "Our results firstly reveal that high glucose and lipopolysaccharide activate ROS/TXNIP/ NLRP3/IL-1β inflammasome signaling in glomerular mesangial cells, suggesting a mechanism by which inflammation may contribute to the development of diabetic nephropathy." (PMID 26881256, 2016). "IL-1β, a critical proinflammatory cytokine, enhances the chemotaxis of inflammatory cells, increases vascular endothelial permeability, and may promote the onset and progression of diabetic kidney disease." (PMID 39201671, 2024). "The subsequent autocleavage and activation of caspase-1 in turn results in the processing of pro-IL-1β to its mature form, which then leads to the induction of other proinflammatory genes, eventually promoting the oxidative stress and inflammation present in diabetic nephropathy." (PMID 26881256, 2016). "Furthermore, IL-1β is also an instigator of the inflammation found in diabetic nephropathy." (PMID 26881256, 2016).
diabetic nephropathy (continued). "In a rat model of diabetic nephropathy, maresin-1 exerted a protective effect on glomerular mesangial cells by decreasing the expression of ROS, NLPR3, caspase-1, and IL-1β, which are responsible for the development of diabetic nephropathy." (PMID 40731875, 2025). "Piperine and its derivatives significantly alleviate the conditions of diabetic nephropathy by decreasing the signaling of TNF-α, NLRP3 inflammasome, NF-κB, and IL-1β in a diabetic rat model." (PMID 38200253, 2024). "The production of Interleukin-1β (IL-1β) and Tumor Necrosis Factor-alpha (TNF-α) was significantly increased in the glomeruli of diabetic nephropathy (DN) mice." (PMID 37638046, 2023). "In STZ-induced diabetic nephropathy mice, APF also decreased the mRNA and protein expression of inflammatory factors such as TNF-α, IL-1-β, and IL-6, and also improved the damage of high glucose to renal mesangial cells by regulating autophagy." (PMID 37101717, 2023). "The expression of miR-93-5p was shown to be decreased in diabetic nephropathy, again under the regulation of lncRNA, and its inhibition reduced fibrosis and inflammation with a reduction in TNF-α, IL-6, and IL-1β." (PMID 36499023, 2022). "In a mouse model of diabetic nephropathy, maresin-1 exerted a protective effect on glomerular mesangial cells by decreasing the expression of ROS, NLPR3, caspase-1, and IL-1β, which are responsible for the development of diabetic nephropathy." (PMID 35163291, 2022). "For instance, inhibiting the levels of inflammatory cytokines including IL-6, IL-1b, and TNF-α in PRAT through upregulation of heme oxygenase system reduced renal inflammation and ameliorated diabetic nephropathy in rats." (PMID 34298949, 2021). "Another study reported that the KD of miRNA-21 using a specific inhibitor of it decreased the expression levels of pro-inflammatory cytokines such as IL-1β and TNF-α, and alleviated kidney damage in STZ-induced diabetic nephropathy rats." (PMID 33193581, 2020). "Inflammatory cytokines, such as IL-1β and TNF-α, and chemokines, including MCP-1 and ICAM-1, have been shown to contribute to the development of diabetic nephropathy." (PMID 30841605, 2019). "Inhibiting oxidative stress and inflammatory reactions associated with apoptosis, significantly reduceing levels of Caspase-1, IL-1β, and NLRP3 and improving GBM thickening and inflammatory cell infiltration, thereby suppressing the development of diabetic nephropathy." (PMID 40568564, 2025). "Tripterygium glycosides is proved to not only regulate inflammatory factors such as TNF-α, IL-1β and TGF-β1, but also ameliorate podocyte injury and glomerular hypertrophy, reduce urinary protein in rats with diabetic nephropathy through anti-inflammation and inhibition of macrophage infiltration." (PMID 39898319, 2024). "Furthermore, increased in renal biopsies of people with diabetic nephropathy, NLRP3 and IL1β expression and activity is also reportedly increased in people with tubulointerstitial injury as compared to those without." (PMID 35755447, 2022). "Inflammatory cytokines such as IL-1β, IL-18, TNF-α, MCP-1, and ICAM-1 are significantly increased in renal tissues during diabetic nephropathy and attenuating the expression of these cytokines may protect against diabetic renal injury." (PMID 26881256, 2016). "In a rodent model of DM and diabetic nephropathy, MSC treatment ameliorated diabetic nephropathy via inhibition of MCP-1 expression by secreting HCP, thus reducing macrophage infiltration and down-regulating Il-1β, IL-6, and TNF-α expression in the renal tissue of diabetic rates." (PMID 24936198, 2014). "In patients with diabetic kidney disease (DKD), the expression levels of IL-1β, IL-18, and NLRP3 were significantly increased in renal biopsy samples, correlated with the aggravating of albuminuria, suggesting that inflammasome may play a critical role in the progress of DN." (PMID 37056456, 2023).
dermatitis (81 papers, 2013 to 2025). An inflammatory process affecting the skin. "In fact, deficiency or inhibition of IL-1β or CXCR2 has been reported to suppress the onset of dermatitis." (PMID 41296413, 2025). "The pro-inflammatory cytokine IL1β induces the outcome of AD skin inflammation through qualitative changes associated with epidermal homeostasis." (PMID 39199350, 2024). "TNF-α contributes to early skin inflammation and activates keratinocytes, and thus, causes epidermal hyper-proliferation, and IL-1β amplifies inflammatory response and promotes hyperkeratosis." (PMID 39684888, 2024). "IL-1β and its signaling pathway were specifically found to be associated with the development of AD-like dermatitis lesions." (PMID 37248497, 2023). "Compared with WT mice, KO mice showed an increased susceptibility to P. acnes-induced skin inflammation, as evidenced by higher levels of pro-inflammatory factors such as Cxcl1, Il-1α, Il-1β, Il-6 and Tnf-α in the knockout mice." (PMID 35414779, 2022). "They noted upregulation of IL-1α, IL-1RA, TNF-α and IL-1α /IL-1RA ratios, as well as time-dependent increase of IL-1B and observed some differences in the inflammatory mechanisms of incontinence-associated dermatitis, depending on the moisture source." (PMID 36555871, 2022). "MMP-9 also cleaves extracellular matrix components and causes skin inflammation via activation of cytokines, including IL-1β and IL-1349." (PMID 35697899, 2022). "While IL‐1α deficiency did not decrease the inflammatory score of Flgft/ft mice (P = 0.942), IL‐1β‐deficient Flgft/ft mice were protected from the development of skin inflammation (P = 0.013)." (PMID 30937919, 2019). "Dermatitis is characterized as a potent form of skin inflammation associated with an elevated level of IgE and the activation of IL-1β." (PMID 26104582, 2015). "Dermatitis is a common manifestation of autoinflammatory diseases in human beings in particular those that are associated with overexpression of IL1B (inflammasomopathies) and with defects in the NFKB signaling pathways." (PMID 24465642, 2014). "In sum, our study reveals that filaggrin deficiency in the appropriate genetic background leads to spontaneous dermatitis associated with increased IL1β, Th2-related cytokines and activated NFκB signalling." (PMID 23844115, 2013). "Therefore, IL-36 is likely to be an important diagnostic tool for dermatitis, and additional keratinocyte-linked cytokines like the inflammasome-related IL-1β, IL-36α, and IL-36γ should be investigated in the future." (PMID 32076123, 2020). "As hypothesized, IL-1β deficiency in Sharpincpdm mice significantly delayed the onset of dermatitis." (PMID 27892465, 2016). "Furthermore, to substantiate the pathogenic role of IL-1 in dermatitis and wasting syndrome, we treated normal healthy mice with recombinant IL-1α or IL-1β." (PMID 25119884, 2014). "The results showed that CBG improved dermatitis severity score, epidermal thickness, and mast cell count and reduced inflammatory cytokines (Tslp, Il1b, Il4, Il6, Il13, Il17, Il18, Il22, and Il33) by qRT-PCR (p < 0.001)." (PMID 39851511, 2025). "Recent research highlights that IL-1β plays a fundamental role in driving skin inflammation in atopic dermatitis." (PMID 41304926, 2025). "Enhanced cleavage products of caspase-1, GSDMD, and IL-1β were observed in both imiquimod-induced psoriasis-like dermatitis (IIPLD) mouse epidermis and M5 (simulating psoriatic inflammatory challenge)-treated keratinocytes in vitro." (PMID 40332377, 2025). "Additional processes contribute to the dermatitis caused by the cpd mutation of Sharpin, including TLR3 signaling, NLRP3 inflammasome and IL-1β signaling, and IL-4 signaling." (PMID 38156288, 2024). "The production of interleukin (IL-1β) and other inflammatory cytokines is crucial in skin inflammation." (PMID 39338343, 2024).